IL10 (interleukin 10)
Diseases named in the same sentence as IL10 in open-access papers (continued):
Sharing a sentence is not in itself a finding about the gene and the disease.
cancer (continued). "In the current study, cancer cell-conditioned medium and IL-10 induced higher expression levels of CD14, CD16 and CD163 with normal DC markers, including CD11c and CD209." (PMID 25013476, 2014). "Several inflammatory mediators, such as TNF-α, IL-6, TGF-β, and IL-10, have been shown to participate in both the initiation and progression of cancer." (PMID 24901008, 2014). "From this analysis, it is distinctly indicated that people's taking of the probiotics with the highest ratio of IFN-γ/IL-10 leads to a significant increase in their NK cytotoxicity against K562 cancer cell line." (PMID 25759833, 2014). "We focused on the IL-10 centered network, as IL-10 is a well-known cytokine with an anti-inflammatory activity and relation to cancer." (PMID 25056661, 2014). "Treatment with p38i (SB203580) prior to TDL pulsing restored the ability of myDC to secrete IL-12 in 6/8 cancer patients and still suppressed IL-10 in all donors." (PMID 23901045, 2014). "Westernized diets are also low in vitamin D, a nutrient that when present normally works together with IL-10 to protect against inflammatory disorders and even some types of cancer." (PMID 24392159, 2014). "Interleukin-10 (IL-10) is a multifunctional cytokine which participates in the development and progression of various malignant tumors." (PMID 23460834, 2013). "We next examined Treg and cancer cells for a detailed expression analysis of Foxp3, IL-10, and TGF-β by immunohistochemistry." (PMID 23382847, 2013). "Direct inhibition of myeloid DC differentiation mediated through IL-10 and IL-6 was proposed to induce a potentially immunocompromising microenvironment in cancer patients." (PMID 23616009, 2013). "Westernized diets are also low in vitamin D, a nutrient that normally works together with IL-10 to enforce immune tolerance and protect against inflammatory disorders and some types of cancer." (PMID 23874682, 2013). "The usage of IL-10 blockade represents a useful strategy for successful treatment of cancer in preclinical settings." (PMID 23663506, 2013). "Interleukin-10 (IL-10) is a multifunctional cytokine which participate in the development and progression of various malignant tumors." (PMID 23460834, 2013). "The network of pro-inflammatory cytokines such as regulated upon activation normal T-cell expressed and secreted (RANTES), interleukin (IL)-10, and IL-8 have been proposed as mediators of cancer development." (PMID 23566546, 2013). "Recently, pro-inflammatory cytokines, such as regulated upon activation normal T cell expressed and secreted (RANTES), interleukin (IL)-10 and IL-8 have been proposed as mediators of cancer development." (PMID 23566546, 2013). "Several groups observed Foxp3 expression by various cancer types and its potential role on immune surveillance by producing immunosuppressive cytokines such as IL-10 and TGF-β." (PMID 23382847, 2013). "IL-10, a potent pleiotropic cytokine, has the dual ability to immunosuppress or immunostimulate anti-cancer properties." (PMID 22436502, 2012). "Contrary, M2 or “alternatively activated macrophages”, which are induced in vitro by IL-4, IL-10, and IL-13, are known to support angiogenesis and inhibit anti-cancer immunity through the production of TGF-β and IL-10." (PMID 23109839, 2012). "Persistent HPV infection, along with environmental and genetic factors such as IL-10, predisposes individuals to SICL and subsequent progression to cancer." (PMID 23148667, 2012). "It has been shown previously that cancer cells expressing PD-L1 on their surface secrete immunosuppressive cytokines Galectin-1, IL-6, IL-10, and TGF-β, which can inhibit cytotoxic CD8+ T cells." (PMID 22496728, 2012). "Cancer cells can drive immune suppression by multiple mechanisms, including the secretion of immune-suppressive cytokines and chemokines, such as TGFβ and IL-10, or FasL expressing microvesicles (TMV) which induce lymphocyte apoptosis." (PMID 22046194, 2011).
cancer (continued). "The investigators demonstrated that the ability of Tregs to inhibit or suppress cancer was highly dependent upon the type of gut bacteria and IL-10." (PMID 21818290, 2011). "Day 14 cultured DC produced higher amount of IL-12 than IL-10 which allow to expecting the induction of stronger Th1 cellular immunity desirable for cancer vaccine." (PMID 22013914, 2011). "In all IL-10−/− carcinomas (n = 4), membranous beta-catenin localization was found, while this was the case for two out of 16 AOM/DSS-induced tumors." (PMID 21799775, 2011). "CIN was detected in 81.25% of all murine CACs induced by AOM/DSS, while all carcinomas that arose in IL-10−/− mice were chromosomally stable." (PMID 21799775, 2011). "Elevated IL-10 levels have been found in a variety of human malignant tumours and are an independent prognosis factor for decreased response to chemotherapy in patients with advanced gastrointestinal malignancies." (PMID 20836854, 2010). "On the other hand, several animal experiments have shown diverse effects regarding the influence of IL-10 on the cancer immune response." (PMID 19040745, 2008). "In this study, we have analysed the expression of IL-10 in 25 of 28 carcinoma specimens and in 29 of 30 NHPG specimens." (PMID 17325703, 2007). "Interleukin-10 was detected mostly in glandular epithelium in PAC of 14 out of 25 of carcinoma specimens (66%), in peri-PAC of eight out of 25 of carcinoma specimens (33%) and in NHPG of nine out of 29 of NHPG specimens (30%)." (PMID 17325703, 2007). "None of parameters measured in this study (MVD, percentage of CD54-expressing vessels, clustered infiltrates and IL-10 production) correlated with grade of carcinoma, serum PSA levels and patient's age." (PMID 17325703, 2007). "It was postulated that interleukin 10 production in malignant tumors would facilitate their escape from immune surveillance." (PMID 15450122, 2004). "In fact, LPS-induced upregulation of CD80, CD86 and CD83, and the expression of IL-10 were similar in cancer patients and healthy controls." (PMID 14562018, 2003). "The percentage of DCs expressing cytoplasmic IL-10 was significantly higher in cancer patients in unstimulated conditions (3.70 ± 0.35 vs 2.65 ± 0.22%, P=0.046), while it was similar to control subjects upon LPS stimulation." (PMID 14562018, 2003). "Naing and colleagues found that pegylated IL-10, also known as Pegilodecakin, has the potential to systematically stimulate immune responses in individuals with cancer, notably improving the function of CD8+ T cells and encouraging the expansion of polyclonal T cells." (PMID 41601653, 2026). "A strategy combining TAM‐/TIDC‐targeted delivery with the dual biological functions of let‐7b (as both a TLR‐7 ligand and an IL‐10 inhibitor) may provide a novel approach for cancer immunotherapy." (PMID 41551936, 2026). "TAM produce IL‐10 which improves the viability of cancer cells in NSCLC by stimulating the JAK1/STAT1/NF‐κB/Notch1 signaling pathway and promoting the expression of SOX‐2 and other genes linked to cancer cells." (PMID 39927632, 2025). "In addition to CCL2, CCL22, and IL-10, TAM-associated markers CCL5 and SPP1 (secreted phosphosprotein 1, also known as osteopontin, OPN) are promising targets for novel cancer immunotherapy." (PMID 40806751, 2025). "Based on these excerpts from the literature, the high IL-10 levels found in the patients in our study are another point of concern that may indicate cancer recurrence." (PMID 40725135, 2025). "Preclinical advances for IL-10–based strategies in cancer immunotherapy." (PMID 40149345, 2025). "The role of TGF‐β, TNF‐α, IL‐10, IL‐6, and chemokines is more complex, as they may promote or inhibit cancer in a context‐dependent manner." (PMID 40356340, 2025). "High IL-10 concentrations were predictive of cancer recurrence." (PMID 41155334, 2025).
cancer (continued). "In response to classic chemotherapy, cancer cells, like melanoma cells, secrete more EVs able to restart cancer growth in in vivo systems, specifically by enhancing arginase 1 and IL10 in stromal cells and stimulating the transcription of genes involved in the DNA repair process." (PMID 40806235, 2025). "The cancer-related need for support, combined with the mechanisms described in the “erosion model”, likely accounts for the positive correlations observed between the support-based coping strategies and IL-17a and IL-10 at T2 in the total sample." (PMID 41153842, 2025). "Accordingly, a combination approach involving IL-10 and C3aR/C5aR antagonists could serve as an effective therapeutic strategy for immune-resistant cancers, particularly when augmented with the addition of IL-2 [IL-10 + IL-2 + C3aR/C5aR signaling blockade]." (PMID 40149345, 2025). "PD-L1 is commonly expressed on T-cells, B-cells, macrophages, cancer cells, and DCs and is upregulated through the release of pro-tumor cytokines (such as interleukin-4 (IL-4), IL-10, and vascular endothelial growth factor (VEGF)) from cancer cells and is associated with poor prognosis." (PMID 40356923, 2025). "Regular PA stimulates the release of skeletal muscle-derived IL-6, which inhibits the release of pro-inflammatory factors (TNF-α and IL-1β) and promotes the release of the anti-inflammatory factor IL-10, inducing an anti-inflammatory environment and improving health outcomes in cancer survivors." (PMID 39896788, 2025). "Epigenetic reprogramming of immune cells can be triggered by factors secreted by cancer cells such as the cytokines, Interleukin-10 (IL-10) and Transforming Growth Factor Beta (TGF-β), as well as by physical properties of the TME, such as hypoxia, and the extracellular matrix (ECM)." (PMID 41154396, 2025). "As research progresses, harnessing IL-10’s immunomodulatory capabilities may pave the way for more effective, durable, and personalized cancer treatments." (PMID 40149345, 2025). "This aligns with findings from a network meta-analysis in cancer patients showing that combined aerobic and resistance training was superior to single-modality exercise in reducing inflammatory markers such as IL-6, IL-8, IL-10, TNF-α, and CRP." (PMID 41583457, 2025). "In this regard, we were particularly interested in the significant CDDO-2P-Im-dependent downregulation of IL10 and TGFβ signaling, as both of these pathways have immunosuppressive functions which may inhibit the anti-cancer immune response." (PMID 40890297, 2025). "They produce IL-10 and suppress T cell responses, promoting cancer progression." (PMID 40136652, 2025). "Furthermore, the release of IL-10 has been shown as the most often occurring Breg cell effector mechanism in human cancer." (PMID 40297580, 2025). "IL-10's role as a key immunosuppressive cytokine in cancer is well established." (PMID 41179937, 2025). "The description of SFB-specific Tr1-like cells in the small intestine was surprising, as this CD4+ T cell subset, characterized by abundant IL-10 secretion in the absence ofFoxp3expression, has only been described in the context of chronic antigen stimulation, such as chronic infection or cancer." (PMID 40747421, 2025). "Additionally, Pellino1-mKO mice treated with AOM/DSS showed lower levels of IL10 known to promote immune evasion and contribute to cancer progression." (PMID 39893188, 2025). "This review critically examines recent progress, ongoing challenges, and emerging advancements in IL-10-directed cancer immunotherapy, highlighting the need for refined delivery strategies, enhanced intratumoral targeting, and synergistic combination approaches." (PMID 40149345, 2025). "In terms of prognosis, high IL-10 generally portends a worse outcome in cancer." (PMID 41007766, 2025). "However, the role of circRNAs has been studied only in the context of IL‐6 and IL‐10 signaling in cancer." (PMID 40356340, 2025).
cancer (continued). "Additionally, elucidating the interplay between IL-10 and other immunoregulatory pathways will provide valuable insights into its broader applicability across various cancer types." (PMID 40149345, 2025). "These compounds have the ability to block T cell activity, increase the production of immune suppressor molecules like transforming growth factor-β(TGF-β), vascular endothelial growth factor, and interleukin-10(IL-10), leading to the eventual spread of cancer cells." (PMID 40145100, 2025). "We analyzed pan-cancer expression and prognostic value of IL-10 and TGF-β1 via TCGA/GTEx databases." (PMID 41438510, 2025). "Given these contradictory roles, IL-10 remains a complex candidate for cancer immunotherapy." (PMID 40868199, 2025). "Interestingly, significantly higher levels of IL‐10 were observed in the brains of mice in which cancer cells were rejected (CANReject) when compared to CANTumor (p = 0.013) or CANRegress groups (p = 0.014)." (PMID 40172096, 2025). "Cancer cells create an immunosuppressive microenvironment that impairs both innate and adaptive immune responses, partly through the secretion of immunosuppressive cytokines such as interleukin-10 (IL-10) and transforming growth factor beta (TGF-β)." (PMID 40486875, 2025). "As research continues to refine IL-10 therapies, innovative delivery systems and combination treatments could unlock its full potential in precision cancer care, making IL-10 a key player in the future of immunotherapy." (PMID 40149345, 2025). "Moreover, hypoxia, soluble factors (such as HIF-α, TGF-β, IL-10, and IL-27) and cancer-derived circRNA present in the TME have been shown to induce ICs expression on T cells." (PMID 40607422, 2025). "IL-10 has been identified as a key player in promoting radioresistance in cancer cells." (PMID 39682192, 2024). "Nevertheless, immunoregulatory cytokines such as IL-10 and TGFβ may be secreted by some cancer cells during cell culture, therefore producing a more tolerogenic phenotype on DCs, a possible obstacle rather than an advantage." (PMID 38962577, 2024). "The anti-inflammatory effects of IL-10 have led to the hypothesis that IL-10 might undermine immune responses against cancer." (PMID 39000453, 2024). "The role of IL-10 in cancer remains a subject of controversy." (PMID 39204319, 2024). "By modulating the immune response, IL-10 may help regulate the body’s ability to recognize and eliminate cancer cells." (PMID 38248028, 2024). "Therefore, understanding the function of EBV IL-10 is important in both virology and cancer biology." (PMID 39459945, 2024). "Additionally, IL-10 is a key cytokine involved in CC evolution by regulating the transcription of immune cells, preventing the killing of cancer cells, and promoting the occurrence, development, and metastasis formation in CC." (PMID 39459945, 2024). "Therefore, in the present study, the high expression of IL-10 in the HCC group and its rapid decrease after surgery suggested that IL-10 can be secreted by cancer cells, and its dynamic changes before and after surgery can be used for prognostic evaluation." (PMID 38693593, 2024). "IL-10 is considered one of the very promising targets for immunotherapy; however, its controversial role in carcinogenesis hinders the applicability of benefiting from its blockade in cancer treatment (Ref." (PMID 38186186, 2024). "Several research endeavors have indicated the possible involvement of IL-4, IL-10, and IL-13 in mitigating the aggressive characteristics of cancer within bone structures, underscoring their viability as pharmacological targets for the management of bone metastases." (PMID 39125732, 2024). "Altogether, strategies that reduce MDSC-derived IL-10, whether through inhibiting upstream pathways or directly neutralising IL-10, is likely to be beneficial in the treatment of a range of human cancers." (PMID 38464388, 2024). "Increased Th2 cells promote cancer growth and metastasis by producing IL-4, IL-5, and IL-10." (PMID 38293522, 2024).
cancer (continued). "In some cases, IL-10 has been investigated for its potential role in cancer immunotherapy." (PMID 38248028, 2024). "There is some evidence that IL-10 blockade, coupled with standard ICIs, has synergistic effects in various cancer models including OC; hence, targeting the IL-10 pathway combined with ICIs may represent a potential treatment strategy in OC." (PMID 39199610, 2024). "Additionally, the anti-inflammatory properties of Interleukin-10 (IL-10) are also related to its ability to inhibit M-CSF, potentially opening up new avenues for its application in cancer treatment." (PMID 38646440, 2024). "Is IL-10 blockade a possible option as a novel immunotherapeutic approach for cancer patients?" (PMID 38186186, 2024). "This highlights the promising role of such circRNAs as novel immunotherapeutic molecules that could ablate IL-10 production and act as a powerful immunomodulatory anti-cancer treatment for several cancer patients." (PMID 38186186, 2024). "IL-4 and IL-10 cytokines are upregulated in premalignant and cancer lesions." (PMID 39599846, 2024). "Recent studies identified cancer stem cells as a possible source of IL-10." (PMID 38279997, 2024). "IL10 can be produced by both immune cells and (breast) cancer cells." (PMID 38711262, 2024). "Meanwhile, the destroyed bacteria and cancer cells can activate immune cells (such as macrophages, neutrophils, and dendritic cells), which release inflammatory cytokines (TNF-α and IL-1β) and reduce anti-inflammatory cytokines (IL-10), thereby further enhancing the efficacy of cancer immunotherapy." (PMID 38472176, 2024). "Besides, circulating inflammatory cytokines, e.g., TNF-α, IL-6, and IL-10 are discussed as potential prognostic oncomarkers in BC patients due to their contribution to cancer proliferation and invasion." (PMID 38464730, 2024). "High neutrophil levels in tissues secrete numerous inflammatory mediators like vascular endothelial growth factor (VEGF), tumor necrosis factor-a (TNF-a), interleukin-2 (IL-2), interleukin-10 (IL-10), and interleukin-6 (IL-6) which creates a suitable environment for cancer progression." (PMID 38166889, 2024). "In contrast, GATA3 and IL-10 dominated to suppress the Th1 phenotype toward cancer progression." (PMID 38279220, 2024). "Additionally, there appears to be a correlation between vitamin D and other inflammatory factors such as TNF-alpha, IL-1 beta, IL-6, IL-8, and IL-10, as well as its involvement in autoimmune diseases and cancers." (PMID 38337827, 2024). "Furthermore, the circLOC729852/miR‐769‐5p/IL‐10 axis is an attractive therapeutic target in M2 macrophage‐driven cancers." (PMID 38506082, 2024). "IL-10 is produced by a wide variety of cells and it exhibits highly pleiotropic effects that may play a dual role in cancer initiation and development." (PMID 38785507, 2024). "However, as tumors grow, the release of prostaglandins-E2 (PGE2) and IL-10 by cancer cells hinders the immune responses mediated by M1 proinflammatory cytokines." (PMID 39796695, 2024). "The mechanism may be that MDSC produces IL-10, which in turn promotes cancer initiation by regulating the STAT3-DNMT3b-IRF8 axis." (PMID 38319729, 2024). "In addition to IL-10, another protein with anti-inflammatory, antioxidant, and anti-cancer properties involved in cancer biology is known as Klotho." (PMID 38337668, 2024). "It remains unclear whether SNPs in the IL-10 or its receptor account for the varying effects of IL-10 inhibition on cancer treatment." (PMID 38186186, 2024). "The function of IL-10 in cancer development, however, is subject to debate due to its dual effects." (PMID 39132165, 2024). "In other cancers, such as ovarian cancer, PCPE2 expression in tumor-associated macrophages was found to contribute to cancer progression along with enhanced ECM reorganization and elevated ascites levels of interleukins 6 and 10 (IL-6 and IL-10)." (PMID 39374805, 2024).